NOX1 (NADPH oxidase 1)
Diseases named in the same sentence as NOX1 in open-access papers (continued):
Sharing a sentence is not in itself a finding about the gene and the disease.
Stroke (continued). "Therefore, in order to find a microenvironment promoting the survival of newborn cells in ischemic neurogenesis, we determined the role of Nox1 in I/R-induced oxidative damage and the effect of Nox1 on the survival of newborn cells in ischemic neurogenesis after stroke." (PMID 25617620, 2015). "Our data suggest that Nox-1 may be responsible for oxidative damage to DNA, subsequent cortical neuronal degeneration, functional recovery, and regulation of ischemic neurogenesis in the peri-infarct regions after stroke." (PMID 25617620, 2015). "The role of NOXs in post-stroke functional recovery is particularly evident when examining the effects of NOX2, NOX1, and the influence of age." (PMID 39334724, 2024). "Therefore, Nox1 may serve as a potential therapeutic target for brain repair after stroke." (PMID 25617620, 2015). "To establish any potential specificity of this function for NOX4 compared to NOX1 and NOX2 in stroke, we carried out identical experiments in 6- to 8-wk-old Nox1y/− and Nox2y/− mice." (PMID 20877715, 2010). "In addition, expression of NOX1, NOX2, and NOX4 significantly increases in brain tissue and the cerebral vasculature after stroke, and these enzymes are a substantial source of pathological ROS following intracerebral hemorrhage." (PMID 36793787, 2023). "VAS2870 did not display an additional protective effect in NOX4 knockout mice, whereas it did so in WT mice, further suggesting that NOX1 and 2 have no major implication in stroke pathology." (PMID 22625431, 2012). "The role of Nox1 in mediating neuroprotection following stroke is not well understood." (PMID 30816157, 2019). "Similarly, no protection (although no worsening) from experimental stroke was described following tMCAO in NOX1 KO mice in a further study." (PMID 26785066, 2014).
gastric cancer (13 papers, 2019 to 2025). A primary or metastatic malignant neoplasm involving the stomach. "NADPH oxidase 1 (NOX1)-induced reactive oxygen species (ROS) signaling contributes to gastric cancer development and stemness through effects on the TNFα/NF-κB pathway." (PMID 33406733, 2021). "Twelve percent of gastric carcinomas, 4% of breast carcinomas, and 2% of prostate carcinomas were scored as high NOX1 expressers (2+ and 3+)." (PMID 32428030, 2020). "Here, we examined the role of NOX1 in stomach tumorigenesis using mouse models as well as gastric cancer cells." (PMID 30700829, 2019). "Accordingly, NOX1-induced ROS signaling has a possible role in increased proliferation of epithelial cells of gastritis and gastric cancer." (PMID 30700829, 2019). "We also found that NF-κB directly regulated NOXO1 expression in TNF-α-stimulated gastric cancer cells, suggesting that inflammation induces NOX1 complex activation through TNF-α/NF-κB pathway." (PMID 30700829, 2019). "Another study demonstrated that IL-17A can inhibit apoptosis and promote ROS production, sphere formation ability of cancer stem cells, and expression of stemness-related genes in gastric cancer AGS cells through the regulation of the IL-17RC/NF-ᴋB/NOX1 pathway." (PMID 38075398, 2024). "Therefore, inhibition of the NOX1/ROS signaling pathway is a possible strategy for prevention and therapy for gastric cancer development." (PMID 30700829, 2019). "IL-17RC is upregulated in helicobacter pylori-induced gastric cancer tissues and human cancer tissues, participating in the IL-17A/IL-17RC axis and modulating the development of GC through the NF-κB/NOX1 signaling pathway." (PMID 39906741, 2024). "Therefore, targeting NOX1 complex or downstream ROS signaling in addition to H. pylori eradication may be a potential strategy for prevention of gastric cancer." (PMID 30700829, 2019). "Our findings indicate that IL-17A promotes gastric cancer growth, oxidative stress, and CSC stemness by regulating the IL-17RC/NF-κB/NOX1 pathway." (PMID 36125689, 2023). "The human gastric carcinoma cell line MKN-45 is a prototype of bona fide tumor cells, as it is protected from the NADPH oxidase-1 (NOX-1)-driven HOCl- and nitric oxide (NO)/peroxynitrite apoptosis-inducing signaling pathways by a membrane-associated catalase." (PMID 34679719, 2021). "Secondly, IL-17A also activates the NF-κB/NADPH oxidase 1 (NOX1) signaling pathway by binding to IL-17RA and IL-17RC, and promotes the cell cycle transition from G1 to S phase, thereby promoting the proliferation of gastric cancer cells." (PMID 39906741, 2024). "The NADPH oxidase subunit Nox1 is expressed in human gastric cancer cells but not in normal gastric cells." (PMID 36770846, 2023). "In epithelial cells of gastric cancer and gastritis, TNF-α stimuli upregulate NOX1 and the inhibition of NF-κB/P65 by shRNA remarkably blocked the upregulation of NOXO1, which is one component forming NOX1." (PMID 33757467, 2021). "In addition to human MKN-45 gastric carcinoma cells, also human neuroblastoma, Ewing sarcoma and cervical carcinoma cells where shown to respond to CAP treatment with NOX-1 dependent apoptosis induction, mediated by 1O2." (PMID 31578342, 2019). "Further study found that NOS31 could inhibit the proliferation of several colon and stomach cancer cells overexpressing NOX1, while those cells that expressed low levels of NOX1 would not be influenced." (PMID 38576456, 2024). "Moreover, twelve percent of patients with gastric carcinoma had moderate to high NOX1 staining compared to none of the patients with non-malignant gastric inflammatory lesions (p = 0.07)." (PMID 32428030, 2020). "Since Nox1 expression has been shown to be significantly higher in colon and stomach cancers, and non-specific inhibitors such as diphenylene iodonium have issues of specificity and toxicity, we chose ML171 to determine whether apoptosis of AGS cells was blocked upon inhibition of NADPH oxidase." (PMID 36770846, 2023).
Obesity (13 papers, 2012 to 2026). Accumulation of substantial excess body fat. "An association between NOX1, superoxide anion formation and obesity has also been observed in other tissues." (PMID 37627585, 2023). "Obesity was associated with an upregulation of the gene expression of the inflammatory markers Mcp-1 (p < 0.01), IL-6 (p < 0.01), IL-10 (p < 0.01) and Tnf-α (p < 0.001), and with an upregulation of the mRNA levels of Nox-1 (p < 0.05) and Ho-1 (p < 0.001)." (PMID 37239868, 2023). "While Nox-1 has been implicated in the aetiology of obesity and metabolic syndrome, PDI could be relevant in platelet hyperactivation of obese subjects." (PMID 33806982, 2021). "Renal Nox1, Nox2, and Nox4 contribute differentially to vascular oxidative stress-associated ED in obesity, suggesting a need to identify specific Nox subunits as a target, which may result in effective prevention of obesity-related CVD." (PMID 34277732, 2021). "The role of NOX1 in obesity and metabolic diseases depends on the differential expression and localization of NOX1 in different cell types such as endothelial cells, smooth muscle cells and adipocytes." (PMID 37627585, 2023). "Data from this study confirm that both eNOS and NOX1 undergo oscillatory expression in the endothelium, and that in obesity, this axis shifts to favor an increase in NOX1-mediated ROS production and a pro-inflammatory phenotype." (PMID 35600313, 2022). "We and others have consistently demonstrated the pathological effects of glucose on the endothelium in obesity, specifically in regards to imbalance of the eNOS/NOX1 axis." (PMID 35600313, 2022). "Further, microvascular endothelial NOX1 expression was markedly increased in obesity, and moderately upregulated at one time point in lean mice with diurnal disruption." (PMID 35600313, 2022). "Platelet PDI and Nox-1 levels were upregulated in obesity, with platelet Nox-1 also elevated in hypertensive individuals." (PMID 33806982, 2021). "Finally, DCT attenuated the obesity induced-changes in the gene expression of NOX-1 (p < 0.05), NOX-4 (p < 0.01), and GPX-3 (p < 0.05) and DCTE the changes in NOX-1 and NOX-4 (p < 0.05 for both)." (PMID 36139877, 2022). "We also assessed whether the expression of the pro-inflammatory cytokine interleukin-1β (IL-1β), a key factor in the inflammation associated with obesity and metabolic syndrome, was modulated in the heart upon HFHS and by NOX1-deficiency." (PMID 34849611, 2022).
ischemia (12 papers, 2015 to 2025). A hypoperfusion of the BLOOD through an organ or tissue caused by a PATHOLOGIC CONSTRICTION or obstruction of its BLOOD VESSELS, or an absence of BLOOD CIRCULATION. "In ischemia and hypoxia, the reperfusion state after blockage clearance induces NOX1 expression, furthering ischemia-associated tissue damage and BBB disruption." (PMID 39858401, 2024). "A decrease in miR-145-5p and an increase in NOX1, producing superoxide anion, were observed following ischemia/reperfusion injury." (PMID 39684214, 2024). "Nox4 KO reduced infract size after cardiac ischemia-reperfusion and Nox1/4 inhibitor administration played anti-inflammation via reducing ROS level in ischemia retina." (PMID 30571757, 2018). "There was a significant increase in NOX1 level in the ischemia and I/R groups compared to the control group (P=0.044, P=0.001, respectively)." (PMID 30627370, 2018). "A moderate reduction in lesion volume and cerebral edema, and an ameliorated blood—brain barrier (BBB) leakage with relatively mild ischemic damage (60 min ischemia followed by 23 h of reperfusion) was observed after knockout of Nox1." (PMID 25617620, 2015). "In a model of myocardial ischemia-reperfusion injury, 30 min of ischemia followed by 24 h of reperfusion resulted in a significant decrease in the size of myocardial infarct in Nox1-, Nox2-, and Nox1/Nox2-deficient mice, but not in Nox4-deficient mice." (PMID 38396709, 2024). "Additionally, Nox1 expression was also found in neurons, as we have previously showed that Nox1 is upregulated on neurons in response to other in vivo injury paradigms such as ischemia or paraquat and 6-hydroxydopamine (6-OHDA)-mediated neuronal death." (PMID 27260166, 2016). "NOX1 has a large role in neuroinflammation, BBB disruption, and ischemia." (PMID 39858401, 2024). "Although a specific relation of NOX1 and p47phox activation following ischemia in cardiac cells in particular has not been reported." (PMID 29956081, 2018). "Interestingly, no protection was observed in a model of chronic ischemia, strengthening the notion that Nox1- and Nox2-mediated oxidative damage occur during reperfusion." (PMID 38396709, 2024). "In NOX-1, NOX-2 but not NOX-4 knockout mice a significant decrease in the size of myocardial infarct was observed following 30 min of ischemia and 24 h of reperfusion." (PMID 39153251, 2024).
prostate carcinoma (12 papers, 2010 to 2024). A carcinoma that arises from epithelial cells of the prostate gland. "Thus, animal experiments have shown that NOX1 is positively associated with tumorigenesis and malignant behavior in prostate cancer." (PMID 29065504, 2017). "Furthermore, in recent years, in vitro models using adenovirus vectors have shown that NOX1 plays a role in the cell death of prostate cancer cells, and NOX1 has been associated with metastatic potential in a series of cell lines developed from LNCaP." (PMID 29065504, 2017). "Unfortunately, there are few reports on the relationship between NOX1 expression and pathological features in patients with prostate cancer." (PMID 29065504, 2017). "NADPH oxidase 1 (Nox1), an enzyme that produces superoxide (which is in turn dismuted to hydrogen peroxide), is overexpressed in colon and prostate cancer cell lines, while its downregulation reverses tumor growth." (PMID 21792362, 2011). "While Nox1 has been shown to be expressed in human colon and prostate cancers, however, limited studies have demonstrated the involvement of Nox1 in an early step of cell transformation." (PMID 20661536, 2010). "Higher H2O2 levels and increased NOX1 mRNA levels are present in human prostate cancer if compared to those of normal tissue." (PMID 24281116, 2010). "Interestingly, in rat prostate cancer, castration results in dramatic increases in NOX1, NOX2, and NOX4." (PMID 29065504, 2017). "Of these, PRLR has been implicated in the pathology of breast and prostate cancer, NOX1 expression may be increased in prostate cancer with an important role in angiogenesis, cell growth, and tumor pathogenesis, and both AMH and PGF are reported as crucial genes in tumorigenesis." (PMID 35741849, 2022). "NADPH oxidase 1 (NOX1), which is overexpressed in colon and prostate cancers, increases levels of VEGF, VEGF receptor, and matrix metalloproteinase 3 (MMP-3)." (PMID 32645959, 2020). "In animal experiments using nude mice, NOX1 overexpression increased tumorigenesis and tumor growth in DU145 human prostate cancer cells." (PMID 29065504, 2017). "p22phox, a critical subunit of several Nox isoforms (Nox1-4), up-regulates HIF-1α and VEGF expression through Akt and ERK signaling in human prostate cancer." (PMID 27637085, 2016). "It has been shown that the anti-cancer properties of propolis and related flavonoids can prevent VEGF-mediated angiogenesis in prostate cancer by downregulating VEGFR2 and inhibiting the PI3K/Akt/mTOR pathway, as well as downregulating NADPH oxidase 1 (NOX1) and HIF-1." (PMID 39519572, 2024). "Some studies have shown that NOX1 and its transmembrane subunit P22phox and NOX5 are overexpressed in prostate cancer, and downregulated NOX5 expression can inhibit cell proliferation and tumor growth and induce apoptosis of prostate cancer cells." (PMID 34336107, 2021). "In humans, NOX1 mRNA and protein are overexpressed in prostate cancer as compared to non-tumor prostate tissues." (PMID 29065504, 2017). "In particular, superoxide produced by Nox1 have been demonstrated to trigger the development of an angiogenic phenotype, which includes VEGF production, in oncogene-transformed human fibroblasts and in human prostate cancer cells." (PMID 27637085, 2016). "In human prostate cancer cells, the expression of ADAM9 metalloproteinase is likely upregulated by NOX1-derived ROS, and could further promote cancer cell invasion and migration." (PMID 24281116, 2010). "Thus, NOX1, NOX2, NOX4, and NOX5 may be potential targets for therapeutic intervention in prostate cancer." (PMID 34336107, 2021). "Thus, while there is controversy regarding NOX1 expression in prostate cancer cells, NOX1 expression seems to be absent or low in DU145 cells." (PMID 29065504, 2017).
prostate carcinoma (continued). "Furthermore, although some studies have suggested a role for NOX1 in gastric, breast, and prostate cancers, our immunohistochemical evaluation of NOX1 protein revealed that NOX1 was not overexpressed in a large percentage of the tumor specimens we examined with these diagnoses." (PMID 32428030, 2020).
hepatocellular carcinoma (11 papers, 2017 to 2024). A malignant tumor that arises from hepatocytes. "Upon liver injury, NOX1 gene of liver macrophages was activated by damage‐associated molecular patterns secreted by dying hepatocytes to accelerate the development of hepatoma." (PMID 33660944, 2021). "SHMT1 affects the expression of downstream molecules ROS through NOX1 in hepatocellular carcinoma, leading to the production of EMT and MMP2 and ultimately influencing its proliferation." (PMID 38594513, 2024). "Upregulated NOX1 and NOX2 expression is considered to contribute to tissue damage and is consistently associated with poor prognosis in patients with hepatocellular carcinoma." (PMID 34439416, 2021). "There have also been data from humans showing that high Nox1 concentration is an independent predictor of shorter survival after treatment of hepatocellular carcinoma by hepatectomy." (PMID 32635630, 2020). "For example, NOX1 promoted cell metastasis by mediating ROS production in hepatocellular carcinoma." (PMID 33968728, 2021). "In our study, NOX1/4/5 and DUOX1/2 expression was higher in hepatocellular carcinoma tissues than in control normal liver tissues." (PMID 28894215, 2017). "A conceiving study demonstrated a role for Nox1-derived ROS in a hepatocellular carcinoma model in mice and patients lacking Nox1." (PMID 33669824, 2021).
pulmonary hypertension (11 papers, 2014 to 2025). Increased pressure within the pulmonary circulation due to lung or heart disorder. "In support of the importance of Nox1 in vascular processes associated with pulmonary hypertension, our in vivo studies showed that hypoxia-induced pulmonary hypertension and arterial remodeling were ameliorated in Nox1−/− mice but not in Nox4−/− mice." (PMID 27402919, 2016). "Furthermore, hypoxia-induced pulmonary hypertension was attenuated in female NOX1−/− deficient mice." (PMID 34068984, 2021). "When NOX1 expression and activity in monocrotaline-induced pulmonary hypertension in rats was inhibited, pulmonary vascular resistance was reduced and pulmonary hypertension attenuated." (PMID 34068984, 2021). "Nox1-dependent ROS production has also been demonstrated in experimental models of pulmonary hypertension and seems to be especially important in arterial fibrosis and vascular aging in stroke-prone spontaneously hypertensive rats." (PMID 30334629, 2019). "Supporting this, in vivo studies exhibited protection against pulmonary hypertension and remodeling in Nox1−/− mice." (PMID 27402919, 2016). "We identify Nox1 as being particularly important in hypoxia-induced pulmonary hypertension and in 16αOHE1-mediated vascular effects in PAH." (PMID 27402919, 2016). "To investigate the pathophysiological significance of estrogen–Nox–dependent processes in PAH, we studied female Nox1−/− and Nox4−/− mice with pulmonary hypertension." (PMID 27402919, 2016). "To evaluate the pathophysiological significance of our in vitro findings, we extended our studies to an estrogen-dependent mouse model of pulmonary hypertension by examining female Nox1−/− and Nox4−/− mice exposed to hypoxic conditions." (PMID 27402919, 2016). "WT mice exhibited features of pulmonary hypertension when exposed to hypoxic conditions as evidenced by increased RVSP, RV end-systolic pressure, RV end-diastolic pressure and RVH, processes that were attenuated in Nox1−/− mice." (PMID 27402919, 2016).
diabetic nephropathy (9 papers, 2019 to 2023). "GKT137831 is in spite this going through phase 2 clinical trials in diabetic nephropathy targeting NOX1/NOX4 activity." (PMID 34099836, 2021). "In a mouse model of streptozotocin‐induced diabetic nephropathy in ApoE−/− mice, the genetic deletion of NOX4 (but not NOX1), protected mice from structural and functional damage linked to diabetic nephropathy." (PMID 36658776, 2023). "This molecule is a NOX1/4 inhibitor developed to prevent oxidative stress and fibrosis in multiple diseases including primary idiopathic fibrosis, primary biliary cholangitis, and diabetic nephropathy." (PMID 34578395, 2021). "At the same time, excessive peroxide and ROS exist in the kidneys of those with diabetic nephropathy, and NOX1 can derive ROS to positively regulate the activity of protein kinase C (PKC) subtypes in kidney tissue, while the activation of PKC signal will activate downstream NADPH." (PMID 34684716, 2021). "In a cellular model of diabetic nephropathy, 24 h incubation of mesangial (glomerular) cells with 25 mM glucose induces cellular proliferation and excess extracellular matrix, which are triggered by mitochondrial stress stemming from NADPH oxidase 1 (NOX1) activation and ROS generation." (PMID 33233708, 2020).